EGFL6 (EGF like domain multiple 6)
Diseases named in the same sentence as EGFL6 in open-access papers (continued):
Sharing a sentence is not in itself a finding about the gene and the disease.
tumor (26 papers, 2010 to 2025). "In cancer, MAM domain-containing proteins, such as ALK and EGFL6, have been implicated in tumor progression and metastasis." (PMID 40427044, 2025). "Egfl6 induces phosphorylation of Syk to promote activation of IL-10 and Cxcl2 in tumor-associated myeloid cells to drive immunosuppression." (PMID 39312740, 2024). "Tumor-associated endothelial cells express high levels of EGFL6, which controls the development of blood vessels during physiological and pathological angiogenesis." (PMID 39867879, 2024). "The expression of EGFL6, which encodes EGFL6 (a member of the EGF-like superfamily that reportedly promotes tumour cell growth by stimulating angiogenesis), was highly upregulated in TRCs, SMC subclusters and MRCs." (PMID 35332263, 2022). "Clustered stromal cells corresponded to endothelial cells (positive for PECAM1/CD31, VWF), normal fibroblasts (FN1, EGFL6), tumor-associated fibroblasts (TAFs; PDGFRA, ADH1B), and thymic epithelial cells (TECs; KRT19, S100A14)." (PMID 35869073, 2022). "From the data in this research, knockdown of EGFL6 is associated with tumor cell viability reduction as well as reduced ERK and AKT phosphorylation." (PMID 33726836, 2021). "EGFL6 knockdown using siEGFL6 was associated with reduced tumor cell viability as well as ERK and AKT phosphorylation." (PMID 33726836, 2021). "Results showed that the level of EGFL6 in tumor-associated endothelial cells of ischemic tissue was significantly higher than that in corresponding tissue without ischemia." (PMID 32624687, 2020). "EGFL6, as a secreted protein, is highly expressed by tumor-associated endothelial cells and acted on endothelial cells during physiological and pathological angiogenesis to control the development of blood vessels." (PMID 32624687, 2020). "Using The Cancer Genome Atlas pan-cancer data, expression profiles of EGFL6, −7, and −8, and their association with the patient survival rate and tumor microenvironment were analyzed in 33 types of cancers." (PMID 33391349, 2020). "As a high level of EGFL6 was associated with types 1, 2, and 6 infiltration (C1, C2, and C6), EGFL6 was concluded to be a tumor promoter because patients with these types had worse survival with a high proliferation rate and rich TGF β." (PMID 33391349, 2020). "In another report, EGFL6 gene expression was observed significantly increased in tumor-associated endothelial cells in comparison with their normal counterparts." (PMID 23285163, 2012). "This suggests that both IL-10 and Cxcl2 mediate, at least in part, Egfl6-dependent tumor immunosuppression." (PMID 39312740, 2024). "Using ID8 and 2F8c tumor cells, 2 syngeneic models of OvCa, we demonstrated that tumor cell expression of Egfl6 induces tumor growth and inhibits antitumor immune response via accumulation of intratumoral PMN-MDSCs and TAMs." (PMID 39312740, 2024). "Here, we evaluate, for the first time, the impact of EGFL6 on tumor innate and adaptive immune response." (PMID 39312740, 2024). "In this study, we provide evidence that EGFL6, in parallel with its effects on tumor cells, both increases myeloid cell migration and drives the differentiation of macrophages and granulocytes toward an immunosuppressive phenotype." (PMID 39312740, 2024). "Consistent with a role in angiogenesis, tumor expression of Egfl6 increased the number of endothelial cells." (PMID 39312740, 2024). "The number of immunosuppressive CD206+ M2-type TAMs was also higher in Egfl6+ tumors compared with tumor controls." (PMID 39312740, 2024). "Tumor expression of Egfl6 induces the accumulation of intra-tumoral PMN-MDSC and TAM and enhance their immune suppressive activities inhibiting the response to anti-PD-L1." (PMID 39312740, 2024). "In line with the mRNA expression, IHC showed that Cxcl2 was abundantly expressed in non-tumor cells of a-PD-L1- and IgG-treated Egfl6-2F8c tumors compared to their control 2F8c tumors." (PMID 39312740, 2024).
tumor (continued). "The studies presented here indicate that Egfl6 is a potentially novel tumor factor that accelerates migration of MDSCs and TAMs to tumor sites and regulates their functional activities." (PMID 39312740, 2024). "Our data provide mechanistic insights into the oncoimmunologic functions of EGFL6 in mediating tumor immune suppression and identified EGFL6 as a potential therapeutic target to enhance immunotherapy in patients with OvCa." (PMID 39312740, 2024). "To evaluate the impact of tumor cell–expressed Egfl6 on the tumor immune microenvironment, we stably expressed Egfl6 in the 2F8c (2F8c-Egfl6) and ID8 (ID8-Egfl6) murine OvCa cell lines, both of which can be grown syngeneically in C57BL/6J (WT) mice." (PMID 39312740, 2024). "Egfl6+ tumor-infiltrating PMN-MDSCs were found to express higher levels of IL-10 than control tumors." (PMID 39312740, 2024). "Egfl6-expressing tumors display accelerated tumor growth and an increased number of intratumoral immunosuppressive MDSCs and TAMs." (PMID 39312740, 2024). "Immunofluorescence assays indicated that Egfl6 was expressed in both tumor cells and weakly in endothelial cells." (PMID 39312740, 2024). "We first evaluated the 2F8c-Egfl6 model, in which we found that expression of Egfl6 resulted in a significant increase in tumor growth." (PMID 39312740, 2024). "Egfl6 is known to promote tumor angiogenesis and is highly expressed in endothelial cells of human OvCa tissues." (PMID 39312740, 2024). "Using syngeneic 2F8c, ID8, and ID8p53–/– Brca2–/– OvCa mouse models and human OvCa tissue samples, we found that tumor Egfl6 induces the accumulation of intra-tumoral MDSCs and TAMs." (PMID 39312740, 2024). "Recent evidence from human tumor biopsy transcription analysis has shown that EGFL6 mRNA is expressed at high levels in various cancers, including CRC, while levels in normal tissues were nearly undetectable." (PMID 33726836, 2021). "A six-gene risk score, the SCCHN TMI (SCCHN-tumor matrisome index: composed of MASP1, EGFL6, SFRP5, SPP1, MMP8 and P4HA1) was constructed and used to stratify patients into risk groups." (PMID 34830910, 2021). "We conducted an experimental azoxymethane (AOM)-induced mouse model to validate the role of EGFL6 in tumor progression in vivo." (PMID 33726836, 2021). "Based on this identification of the unique role of EGFL6 in tumor angiogenesis, more researchers are focusing on the anti-tumor effect of inhibiting tumor angiogenesis by blocking EGFL6." (PMID 32624687, 2020). "EGFL6 is almost undetectable in normal human tissues but highly expressed in embryos and most tumor tissues." (PMID 32983976, 2020). "Altogether, the work of this review promotes understanding of the role of EGFL6 in tumor development, the mechanism of that action, and the potential of EGFL6 as a therapeutic target for tumor prevention and treatment." (PMID 32624687, 2020). "Noh and colleagues sought to investigate the effects of differential expression of EGFL6 in tumor and wound endothelial cells." (PMID 32624687, 2020). "In this review, we summarize findings that support the role for EGFL6 in tumor proliferation, invasion and migration." (PMID 32624687, 2020). "EGFL6 is highly expressed in certain tumor and fetal tissues, indicating its role as a growth factor." (PMID 32624687, 2020). "EGFL6 has received extensive attention in recent years due to its roles in angiogenesis and tumor occurrence and development." (PMID 32624687, 2020). "Using a tumor vascular model, they found expression of EGFL6 in vascular endothelium is similar to that of tumor cell EGFL6, which can promote the growth of transplanted tumor." (PMID 32624687, 2020). "On the basis of investigations and experiments, we discussed the relationship among EGFL6, −7, and −8 and tumor development and prognosis." (PMID 33391349, 2020).
tumor (continued). "The tumor tissues in the groups E10 and G11 were paraffin-embedded and the sections were immunohistochemically stained with antibodies for EGFL6, FGF-2, PDGFβ, VEGFA, CD31, and LYVE1." (PMID 32983976, 2020). "Several studies suggested that EGFL6 was able to promote the growth of tumor endothelial cells by forming tumor vessels." (PMID 32008086, 2020). "EGFL6 is overexpressed in human tumor cells, has a regulatory role in some oncogenic signaling pathways, and is related to tumor growth, metastasis, and progression." (PMID 32624687, 2020). "EGFL6 peptide was radiolabeled with 111In and analyzed for biodistribution and tumor imaging capabilities." (PMID 26045973, 2014). "A single phage library can contain up to 109 unique peptide sequences, offering a sizeable potential for selection of a peptide fragment of a natural ligand, such as EGFL6, which is thought to be specific to tumor vasculature." (PMID 26045973, 2014). "The high homology between 3-G03 and EGFL6, in addition to the potential tumor vasculature promoting properties of the protein, led to further investigation into EGFL6 expression and peptide characterization." (PMID 26045973, 2014). "An in vivo phage display selection resulted in the identification of a potential tumor vasculature ligand, EGFL6." (PMID 26045973, 2014). "The tumor cell line used for selection, as well as several other cancer and non-cancer cell lines, was probed for mRNA and protein expression of EGFL6." (PMID 26045973, 2014). "Conversely, high expression levels of MEP1A and EGFL6 were associated with better overall survival (MEP1A: hazard ratio (HR) = 0.78, 95% CI: 0.62–0.98, log-rank p = 0.033; EGFL6: HR = 0.65, 95% CI: 0.53–0.81, log-rank p < 0.001), suggesting their potential tumor suppressor roles." (PMID 40427044, 2025). "Notably, in the immune-responsive 2F8c mouse model, tumor Egfl6 expression induces resistance to anti-PD-L1 (a-PD-L1) therapy." (PMID 39312740, 2024). "The combination treatment, Egfl6 NAb and a-PD-L1, was associated with (a) a reduced number of intratumoral PMN-MDSCs and TAMs, (b) reduced PMN-MDSC and TAM secretion of IL-10 and Cxcl2, and (c) increased tumor infiltration of antitumor MHC-II+ macrophages." (PMID 39312740, 2024). "Consistent with this, in an immune ‘hot’ tumor model, Egfl6 expression eliminated response to anti-PD-L1 therapy, while Egfl6 neutralizing antibody decreased the accumulation of tumor-infiltrating CD206+ TAMs and PMN-MDSCs and restored the efficacy of anti-PD-L1 therapy." (PMID 39312740, 2024). "Importantly, when a-Ly6G/Ly6C Ab treatment was suspended, Egfl6+ 2F8c tumors started to grow again faster than 2F8c tumor control." (PMID 39312740, 2024). "To test this hypothesis, we treated 2F8c-Egfl6 tumor-bearing mice with IgG control, a-PD-L1, and Egfl6 NAbs or a combination of Egfl6-NAb and a-PD-L1." (PMID 39312740, 2024). "In the ID8 model, a-Ly6G/Ly6C Ab treatment significantly delayed Egfl6+ tumor growth." (PMID 39312740, 2024). "Importantly, qRT-PCR and immunofluorescence analyses also revealed that double treatment, with both a-Egfl6 and a-PD-L1, reduced tumor expression levels of both IL-10 and Cxcl2." (PMID 39312740, 2024). "Myeloid cells play a key role in Egfl6-induced tumor progression." (PMID 39312740, 2024). "EGFL6 has been previously shown to be involved in migration of endothelial cells and tumor cells." (PMID 39312740, 2024). "a-Ly6G/Ly6C Ab treatment delayed tumor growth in both 2F8c+/– Egfl6 tumor-bearing mouse groups." (PMID 39312740, 2024). "According to these results, we assumed that EGFL6 presumably functioned as a tumor-specific protein and could promote tumorigenesis." (PMID 33726836, 2021). "Moreover, we developed an anti-EGFL6 antibody, EGFL6-E5-IgG, to verify the anti-tumor, anti-metastatic and anti-angiogenic properties in vivo to validate the potential of EGFL6 as a therapeutic target in CRC." (PMID 33726836, 2021).
tumor (continued). "To prove our hypothesis, we analyzed the EGFL6 expression level in patients’ tumor tissues by using IHC staining." (PMID 33726836, 2021). "The EGFL6 gene is highly expressed in embryos and most tumor tissues." (PMID 32983976, 2020). "EGFL6 has the potential to promote tumor growth and metastasis." (PMID 32624687, 2020). "So, EGFL6 participates in tumor angiogenesis through mediated Tie2/PI3K/AKT signals." (PMID 32624687, 2020). "Previous studies have shown that EGFL6 can activate Wnt/β-catenin and AKT/ERK signaling pathways, particularly EGFL6 plays a role in tumor angiogenesis through the ERK/AKT signaling pathway, which is associated with tumor occurrence, growth, and metastasis." (PMID 33391349, 2020). "Results of previous studies indicate that EGFL6 is closely related to tumor development." (PMID 32624687, 2020). "The largest inter-tumor heterogeneity was significantly observed in the expression levels of EGFL6." (PMID 33391349, 2020). "EGFL6 is up-regulated in a variety of tumor tissues and promotes tumor angiogenesis." (PMID 32624687, 2020). "However, this study performed a systematic pan-cancer analysis of EGFL6, 7, and 8, comprehensively describing their characteristics and their importance in tumor research." (PMID 33391349, 2020). "The mechanism of action of EGFL6 in tumor formation and development is a topic of active research." (PMID 32624687, 2020). "Among these, it has been found EGFL6 promotes the angiogenesis in the development of tumor." (PMID 32008086, 2020). "EGFL6 is tumor growth factor produced primarily by tumor endothelial cells." (PMID 29340046, 2017). "Additionally, a peptide with homology to EGFL6 was radiolabeled with 111In and used to image tumor vasculature by SPECT/CT." (PMID 26045973, 2014). "Another reason for low tumor uptake might be differential expression of the receptor for EGFL6 in vitro and in vivo." (PMID 26045973, 2014). "Egfl6 mRNA is upregulated in several transcriptomic analyses of human cancer biopsies, and the protein may play a role in tumor vascularization." (PMID 26045973, 2014). "We found that EGFL6 protein was hardly detected in serum of healthy controls, and also was low in most of tumors, which agreed with its mRNA levels in normal adult tissues and tumor tissues." (PMID 23285163, 2012). "We expanded the survey of EGFL6 gene expression profile in other tumor tissues." (PMID 23285163, 2012). "Taken together, this study demonstrated that EGFL6 could be a potential tumor target in CRC." (PMID 33726836, 2021). "Therefore, it is hypothesized that EGFL6 may be a promising therapeutic target in tumor diagnosis and treatment." (PMID 32624687, 2020). "We also investigated whether serum EGFL6 concentrations were correlated with tumor sizes." (PMID 23285163, 2012). "Through bioinformatic analysis, we identified four MAM domain-containing genes (EGFL6, MEP1A, MEP1B, and MAMDC2) that showed significant differential expression between tumor and adjacent normal tissues in CRC." (PMID 40427044, 2025). "Ly6G+ and F4/80+ cells isolated from Egfl6+ ascites showed higher inhibition of GZMB and IFN-γ secretion compared with myeloid cells isolated from tumor controls." (PMID 39312740, 2024). "Similar to the gene expression analysis of BM CD11b+ cells isolated from Egfl6 mice, CD11b+ cells isolated from 2F8c-Egfl6 tumors displayed higher IL10, Cxcl2, Clec5a, and Ceacam1 gene expression compared with tumor controls." (PMID 39312740, 2024). "Thus, we tested whether Egfl6 expression could impact the tumor response to a-PD-L1 immune therapy." (PMID 39312740, 2024). "Our results indicate that, compared with tumor controls, TAMs infiltrating Egfl6+ tumors exhibited upregulation of Cxcl2, whereas PMN-MDSCs isolated from Egfl6+ tumors showed upregulation of both IL-10 and Cxcl2." (PMID 39312740, 2024).
tumor (continued). "Pericytes play a crucial role in tumor neovascularization; consistently, we observed a strong angiogenic signature (such as for ANGPT2, CAV1, PDGFA, THY1, EGFL6, and GMFG) in pericytes." (PMID 37853464, 2023). "These include EGFL6 (epidermal growth factor-like domain-containing protein-6), an EGF superfamily member related to tumor angiogenesis, growth, metastasis and progression that is also overexpressed in embryos." (PMID 34944751, 2021). "We demonstrated that EGFL6 plays a role in CRC tumorigenesis and tumor progression, indicating that EGFL6 is a potential therapeutic target worth further investigation." (PMID 33726836, 2021). "The single-cell RNA-seq analysis of the SCCHN TMI genes revealed that four of these genes (MASP1, EGFL6, SPP1, and P4HA1) are expressed in subpopulations of fibroblasts, macrophages, T cells and in tumor cells." (PMID 34830910, 2021). "In recent years, several studies have shown that EGFL6, EGFL7, and EGFL8 play a crucial role in the process of tumor growth, invasion, and distant metastasis." (PMID 33391349, 2020). "Currently, studies of EGFL6 in tumor focus on the role of EGFL6 acting through the ERK signaling pathway, affecting the occurrence and development of tumor." (PMID 32624687, 2020). "The SKOV3 control group and the EGFL6 knockout cells E10, G11 (6 × 106 cells per injection) were subcutaneously injected into BALB/C nude mice for tumor formation." (PMID 32983976, 2020). "High correlation was maintained even in the presence of the EGF-like domain multiple 6 (EGFL6), a growth factor which changes ALDH+ cell asymmetric division rates and thereby tumor growth rates." (PMID 29340046, 2017). "Consistent with that and a recent study, depletion of CD8+ T cells did not affect the survival rate of a-Egfl6 + a-PD-L1–treated ID8p53–/– Brca2–/– tumor bearing mice." (PMID 39312740, 2024). "While S100A9, IL-10, and Cxcl2 expression was reduced in a-PD-L1-treated 2F8c tumors compared to tumor controls, no reduction was detected between a-PD-L1-treated and control Egfl6+ tumors." (PMID 39312740, 2024). "Treatments with Egfl6 NAbs alone modestly reduced tumor growth but did not affect the probability of survival." (PMID 39312740, 2024). "The data in this research exhibited statistically significant high EGFL6 expression in stage I-IV patient tumor tissues, without expression in non-tumor tissue, in accordance with previous researches." (PMID 33726836, 2021). "NF-kappa B signaling plays a crucial role in inflammation and immune response, which may be an important signal pathway for EGFL6 and EGFL7 to interfere with tumor immunity and tumor stromal cell infiltration." (PMID 33391349, 2020). "Studies have shown that EGFL6 is overexpressed in various tumor tissues, but not expressed or poorly expressed in normal tissues." (PMID 32624687, 2020). "In addition, large differences were observed in the expression levels of EGFL6, EGFL7, and EGFL8 among different tumor types and compared with normal tissues (P < 0.05)." (PMID 33391349, 2020). "In contrast with antagonism of tumor angiogenesis, blocking EGFL6 expression in wound tissue does not affect normal wound healing." (PMID 32624687, 2020). "Results showed that EGFL6 was predominantly expressed in tumor endothelial cells, but not in normal ovary or wound endothelial cells." (PMID 32624687, 2020). "In addition, EGFL6, EGFL7, and EGFL8 were found to be related to immune subtypes and tumor microenvironment." (PMID 33391349, 2020). "EGFL6 is expressed in all major fetal tissues and generally, absent in normal adults tissues, except in tumour of lung and brain." (PMID 27639961, 2016). "A number of fast evolving, placental genes show tumorigenic or tumor suppression activity (ADAM12, ADAMTS18, CAPN6, EGFL6, HTRA4, LIN28B) and others are involved in disorders associated with epithelial and connective tissues (FBN2) or have immune functions (IL1RL1, PRG2, SIGLEC6)." (PMID 26641094, 2015).